BRAF (B-Raf proto-oncogene, serine/threonine kinase)
Diseases named in the same sentence as BRAF in open-access papers (continued):
Sharing a sentence is not in itself a finding about the gene and the disease.
melanoma (continued). "Gene therapy using small RNA interference (siRNA) targeting BRAF presents a promising avenue for melanoma treatment." (PMID 40277680, 2025). "Targeted therapies emerged after discovering melanoma-specific tyrosine kinase receptors like BRAF, which have long served as targets for inhibitors such as vemurafenib and dabrafenib." (PMID 40004731, 2025). "Low serum LDH independently predicts long-term survival of stage IV melanoma patients in every subgroup of treatment type and BRAF status." (PMID 40028330, 2025). "These, in response to BRAF inhibition, can potentiate inhibitor response through a perforin-dependent pathway in a BRAF-mutant melanoma model." (PMID 40872623, 2025). "In melanoma, primary targets such as BRAF, MEK, NRAS, and c-KIT are currently used for targeted therapies." (PMID 40869968, 2025). "To examine the role of PREX2 in melanoma, we interbred BRAF mice with germline deletion of Prex2 (Tyr-CreERT2BrafV600E/+Prex2−/− – henceforth BRAF PREX2)." (PMID 39636745, 2025). "BRAF/MEK inhibitors (encorafenib/binimetinib) achieved a median OS of 33.6 months in BRAF-mutant melanoma." (PMID 41527622, 2025). "The genetic determinants of melanoma occurrence are largely known, highlighting the pivotal role of BRAF serine/threonine-protein kinase as a driver proto-oncogene for the target therapy." (PMID 39859367, 2025). "Mutations in BRAF, NRAS, NF1, and KIT drive overactivation of the Ras/RAF/MAPK/ERK and PI3K/AKT/mTOR signaling pathways, promoting melanoma progression." (PMID 39941158, 2025). "We performed mutation analysis on melanoma samples, identifying TTN, MUC16, and BRAF as the most frequently mutated genes among the top 30 somatic mutations." (PMID 40639089, 2025). "The BRAF-V600E mutation is highly expressed in PCP, and MEK inhibitors have been found to prevent resistance to BRAF inhibitors during melanoma treatment." (PMID 40113789, 2025). "Similar to findings in White melanoma studies, variants in BRAF (25%), NRAS (20%), NF1 (17%), and KIT (17%) were prevalent in Japanese melanomas (Appendix Fig A1B)." (PMID 39823560, 2025). "Although MITF-independent melanocytic cells are unlikely to be the cellular origin of CM in zebrafish models, studies have shown that MITF-independent BRAF-positive melanoma cells are central to disease recurrence." (PMID 40950146, 2025). "In this study, we address this critical knowledge gap by investigating the dynamic evolution of the TME during the transition from tumor regression to residual disease in an immunocompetent mouse model of BRAF‐mutant melanoma." (PMID 40847444, 2025). "For example, KRAS in pancreatic cancer and BRAF in melanoma occur before cell invasion in benign and early lesions." (PMID 40397908, 2025). "This study presents the largest dataset on national melanoma BRAF biomarker status published to date, and the most complete reporting on testing patterns, and characteristics and survival associated with BRAF genotype." (PMID 40902091, 2025). "One of the most pressing challenges in targeted melanoma therapy is the development of resistance to BRAF, MEK, and KIT inhibitors." (PMID 41302945, 2025). "This review aims to systematically explore the molecular basis of resistance to BRAF-targeted therapies in melanoma." (PMID 40872623, 2025). "V-raf murine sarcoma viral oncogene homolog B1 (BRAF) and mitogen-activated protein kinase (MEK) inhibitors are used in treatment of melanoma and other BRAF-mutant tumors." (PMID 40100294, 2025). "To confirm GSK3β upregulation and its activation also on the protein level, we employed Western blot analysis with cell lysates from BRAF-V600E melanoma cells before, during BRAFi treatment and once resistance has developed." (PMID 40184329, 2025). "T-type calcium channel (TTCC) blocker mibefradil can induce apoptosis via autophagy inhibition in drug-resistant BRAF melanoma cells, which provides a therapeutic strategy toward BRAF inhibitor resistance." (PMID 39744692, 2025).
melanoma (continued). "Although our metabolic gene signature was identified in a limited cohort of BRAF-mutant melanoma samples, it provides preliminary evidence for a link between glutamine metabolism and response to targeted therapy." (PMID 40943167, 2025). "It has been observed that BRAF inhibitor-resistant melanomas display increased reliance on glutamine and activate the NRF2 pathway, increasing xCT expression and GSH levels to evade ferroptosis." (PMID 41170386, 2025). "As anticipated, we observed that TRIM63 is significantly phosphorylated in melanoma cells with BRAF V600E compared to those with wild-type BRAF, while the expression levels remained comparable." (PMID 41315179, 2025). "This specifically repressed melanoma and colorectal cancer cells that carried the BRAFV600E or other BRAF mutations." (PMID 39898116, 2025). "Vitiligo is a well-known side effect in patients undergoing treatment for melanoma with either anti-PD-1 immunotherapy or B-Raf (BRAF)/mitogen-activated protein kinase (MEK)-directed targeted therapy." (PMID 39834728, 2025). "The activation of the MAPK and PI3K pathways is nearly universal in melanoma tumors principally due to mutually exclusive mutations in BRAF (40–50% of cases) or NRAS (15–20%) or to the losses of NF1 expression (13%) that may co-occur with BRAF or NRAS mutations." (PMID 40282469, 2025). "This was followed by cobimetinib in 2015 (also for BRAF-mutant melanoma), selumetinib in 2016 for advanced thyroid cancer, and binimetinib in 2018." (PMID 41294711, 2025). "Detection and utility of predictive biomarkers have shown clinical improvement and survival benefits for matched targeted therapies in several types of malignancies (BRAF in melanoma or EGFR in non-small cell lung cancer)." (PMID 40075591, 2025). "Targeted therapies, such as vemurafenib and dabrafenib, have shown remarkable efficacy in patients with BRAF-mutant melanoma; however, resistance often develops due to the activation of alternative signaling pathways or the emergence of resistant subclones." (PMID 41034991, 2025). "The most frequently used targeted therapies for mucosal melanomas are BRAF and MEK inhibitors, which can be administered in combination, e.g., brafenib plus tramatinib, especially in patients with a BRAF V600 mutation." (PMID 41369373, 2025). "In fact, Portuguese patients with BRAF wild-type melanoma were unable to access the combination therapy (in the 1L or subsequently), limiting their treatment options to use anti-PD-1 and anti-CTLA-4 treatments separately." (PMID 40027067, 2025). "Cancer research brought out that the level of SEMA6A-protein expression has a prognostic significance in BRAF-mut melanoma patients by regulating the remodeling of actin cytoskeleton via inducing a SEMA6A-RhoA-YAP-pathway." (PMID 40353861, 2025). "Among the melanoma patients, the most frequently mutated genes were TTN, MUC16, BRAF, DNAH5, and PCLO." (PMID 40781483, 2025). "Mechanistic studies revealed that this co-formulation upregulated PTEN levels, degraded BRD4, and ultimately downregulated c-Myc to curb the proliferation of BRAF inhibitor (BRAFi)-resistant melanoma cells." (PMID 40284496, 2025). "This paradox is particularly evident in BRAF-mutant melanoma, where these inhibitors effectively target critical oncogenic pathways yet simultaneously increase the risk of cSCC." (PMID 41154417, 2025). "She underwent debulking surgery two months after her initial presentation and pathology confirmed a diagnosis of melanoma, BRAF wild-type." (PMID 39984702, 2025). "BRAF-mutant melanomas are more frequent on the trunk, an intermittently sun-exposed area, compared to other locations." (PMID 41010758, 2025). "MAPK is a key pathway that is involved in melanoma and is activated by several mutation, such as NRAS and BRAF." (PMID 41515546, 2025). "Early evidence suggests ICIs do not significantly impact subsequent FGFRi response, consistent with the findings with BRAF/MEKi in BRAF mutant melanoma." (PMID 40362630, 2025).
melanoma (continued). "Together, these data suggest that BRAF-mutant melanoma cells expressing high levels of NR2F1 tolerate targeted therapy and that tumors develop resistance more quickly." (PMID 40955663, 2025). "For example, MEK inhibitors like trametinib and cobimetinib effectively treat BRAF-mutant melanomas." (PMID 40964172, 2025). "For example, combining AKT inhibitors with BRAF inhibitors has demonstrated synergistic effects in preclinical melanoma models, suggesting a potential strategy for patients with BRAF-mutant melanoma." (PMID 40191195, 2025). "For example, treatment with vemurafenib, inhibiting activity of mutated BRAF, leads to a downregulation of PHF5A in melanoma cells." (PMID 39212334, 2025). "CheckMate-066 established that nivolumab was superior to dacarbazine in previously untreated, BRAF-wild-type melanoma, reporting five-year OS of 39% versus 17%, mainly in cutaneous cases." (PMID 41384184, 2025). "The expanded molecular profiles have redefined the initial classification of the 71 atypical melanocytic tumors in ATS, BRAF-mutated nevus/melanocytoma (BAMS), Spitz melanoma and melanoma with Spitzoid features." (PMID 40870546, 2025). "Preclinical studies support the combination of BRAF or BRAF/MEK inhibitors with immune checkpoint blockade (ICB) in melanoma treatment." (PMID 40361336, 2025). "Cotargeting the MAPK and the PREX2/RAC1/PI3Kβ pathways has remarkable efficacy and outperforms monotherapy MAPK inhibition in BRAF-mutant melanoma, supporting the potential of this combination therapy for treating metastatic melanoma." (PMID 39636745, 2025). "Vemurafenib, a selective BRAFV600E inhibitor, significantly extends progression-free and overall survival in BRAF-mutant melanoma but is limited by acquired resistance and frequent cutaneous toxicities." (PMID 41302945, 2025). "Despite this effect in BRAF mutated melanoma, it conversely increases ERK signaling in melanoma cells exhibiting RAS mutation or wild-type BRAF." (PMID 40141318, 2025). "It triggered early ERS followed by apoptosis and autophagy in a series of melanoma cell lines, including patient-derived melanocytes resistant to BRAF inhibitors, and suppressed the growth of BRAF-resistant melanoma xenografts in mice." (PMID 40650182, 2025). "The discovery of the BRAF oncogene, along with the introduction of BRAFi into clinical practice, has dramatically improved survival rates for patients with BRAF-mutant melanoma, which accounts for approximately 40–60% of cases." (PMID 40872623, 2025). "Projective modeling also illustrated the critical role CGP plays in predicting patient outcomes in two CaUP cases that were refined to melanoma following the detection of the actionable biomarker BRAF V600E." (PMID 40399445, 2025). "Further studies are required to assess these observations in other NRAS-mutant tumor cells in order to generalize the findings and also to explore these alterations in vemurafenib-resistant BRAF-mutant melanoma cells." (PMID 40141318, 2025). "In fact, while the inhibition of BRAF or of combined BRAF/MEK initially reduced the tumor progression in BRAFV600E mutant melanoma patients, the targeted therapy resistance emerged in most of them within 1 or 2 years, via several mechanisms." (PMID 40244045, 2025). "Genetic alterations in the BRAF gene are prevalent in melanomas, thyroid cancers, histiocytic neoplasms, and a small portion of lung and colorectal cancers." (PMID 41340127, 2025). "This discovery sheds light on the intricate molecular pathways involved in conferring resistance to BRAF inhibitors in melanoma cells with dysfunctional PTEN and provides valuable insights into potential therapeutic targets for overcoming this resistance." (PMID 40129883, 2025). "Search terms included combinations of the following keywords: skin cancer awareness, melanoma awareness, melanoma, nevi, moles, melanocytic lesions, pregnant, pregnancy, photoprotection, BRAF inhibitors, and immunotherapy." (PMID 41228319, 2025).
melanoma (continued). "Although concomitant BRAF V600E‐positive cancers, such as lung cancer and hairy cell leukaemia, or malignant melanoma and hairy cell leukaemia, have been reported, Concomitant cancers are extremely rare and may provide important insights into the oncogenic mechanisms involving BRAF V600E mutations." (PMID 39950095, 2025). "Identifying patients with melanomas harboring PTEN alterations allows clinicians to anticipate potential resistance to BRAF inhibitors and to consider alternative or combination therapies." (PMID 40129883, 2025). "Selective BRAF inhibitors, including vemurafenib and dabrafenib, have significantly improved overall and progression-free survival in patients with melanoma." (PMID 41155983, 2025). "Immune checkpoint inhibitors targeting the PD-1/PD-L1 axis have also shown efficacy in treating both BRAF-mutant and wild-type melanomas." (PMID 40002300, 2025). "BRAF p.V600E warranted a combination therapy by dabrafenib–trametinib in patients with melanoma and with low-grade spindle-cell STS." (PMID 41373618, 2025). "The enhanced effect of this combination is explained by the fact that BRAF and MEK inhibitors are associated with an increased expression of melanoma antigens and a denser intratumoral CD8+ T‐cell infiltrate." (PMID 40635600, 2025). "Systemic therapy with immune checkpoint inhibitors or combined BRAF/MEK-targeted therapy is recommended by international guidelines for patients with resected stage IIB to IV melanoma, as well as for those with unresectable or metastatic disease." (PMID 40994966, 2025). "The same proportion of melanomas (6%; n = 3/50) underwent BRAF IHC testing from the West Midlands and Yorkshire and the Humber." (PMID 40902091, 2025). "Multiple studies have found that compared with patients treated with targeted therapy, patients with stage III or IV BRAF mutant melanoma treated with immunotherapy have significantly longer OS." (PMID 40860834, 2025). "Given the recurrence of melanoma while on adjuvant nivolumab and the discrepancy in BRAF testing, the patient presented at our institution seeking a second opinion." (PMID 39940799, 2025). "Six patients with BRAF-mutant melanoma received dabrafenib and trametinib; one remains in remission after 4 years, while three progressed and switched to next-line ipilimumab and nivolumab." (PMID 39859464, 2025). "Centrifugal cell adhesion assay was used to determine the adhesive capacities of resting and proliferative BRAF mutant and BRAF wild-type melanoma cells under vemurafenib treatment." (PMID 40636307, 2025). "BRAF-mutant melanoma cells show higher levels of DUSP6, and its reduction after treatment with BRAFi suggests that loss of negative feedback control over ERK contributes to resistance." (PMID 40872623, 2025). "LKB1 loss contributes to tumor development and progression in several tumor types, including BRAF‐mutant melanoma, under different genetic conditions." (PMID 39115053, 2025). "In BRAF-mutant melanomas, CAF-derived HGF has been implicated in resistance to BRAF inhibitors by reactivating the MAPK signaling pathway, thereby allowing melanoma cells to evade therapeutic pressure." (PMID 40649909, 2025). "A growing body of literature has demonstrated that dysregulation of autophagy contributes to melanomagenesis and progression of BRAF V600-mutant melanoma." (PMID 40457397, 2025). "Research has shown that after melanoma cells develop resistance to BRAF inhibitors, they become more dependent on lipid metabolism." (PMID 40652057, 2025). "The COMBI-i study assessed the safety and early efficacy of combining spartalizumab with dabrafenib and trametinib in advanced BRAF-mutant melanoma." (PMID 41333480, 2025). "Genotype-informed anticancer therapies such as BRAF inhibitors can show remarkable clinical efficacy in BRAF-mutant melanoma; however, drug resistance poses a major hurdle to successful cancer treatment." (PMID 39856157, 2025).
melanoma (continued). "The response rate to BRAF inhibitors in advanced thyroid cancer, however, is only 29—38.5% in BRAF mutant thyroid cancer, a substantially lower rate than is seen with melanoma." (PMID 40869231, 2025). "We selected a panel of melanoma cell lines, harboring either mutated or wild type NRAS/BRAF genes, to investigate SPARC promoter activity." (PMID 40943659, 2025). "One dataset corresponds to Etoposide, while the other involves PLX4720, a drug used in melanoma treatment by inhibiting the BRAF protein, thus preventing cancer cell growth." (PMID 41417875, 2025). "Inhibition of this pathway by MRTFi, CCG-257081 resensitized resistant melanomas to BRAF and MEK inhibitors." (PMID 39917624, 2025). "According to a previous study, reactivation of the MAPK pathway caused by BRAF and NRAS alternative splicing conferred BRAFi resistance in melanoma cells." (PMID 40681872, 2025). "According, DANCR is highly expressed across all four melanoma genomic subtypes (NRAS, NF1, BRAF, and triple negative) in The Cancer Genome Atlas (TCGA) genomic and transcriptomic data and in all melanoma cell subpopulations within a heterogeneous tumour model." (PMID 41336739, 2025). "The study highlighted the emerging role of MEK inhibitors in addressing resistance to BRAF-targeted therapies, forming the basis for combination approaches in melanoma treatment." (PMID 39897423, 2025). "Some resistant melanoma tumors have re-activating mutations in MAPK pathway genes (NRAS, BRAF) and others have mutations in PI3K or RAC1." (PMID 39917624, 2025). "Studies report that BRAF-mutant melanomas are more common in younger patients and mainly refer to the SSM subtype, the trunk region, and patterns of intermittent ultraviolet sun exposure 96-98." (PMID 41049012, 2025). "In studies performed on colorectal cancer patients, LoD ranging from 0.01% to 0.18% and 0.01% for BRAF V600 in melanoma patients were obtained." (PMID 39859576, 2025). "Further validation came from the pivotal BRIM-3 randomized, multicenter phase III trial, which compared vemurafenib with dacarbazine in previously untreated patients with metastatic BRAF-mutant melanoma." (PMID 41302945, 2025). "Somatic mutations in the oncogenes BRAF and NRAS result in activation of the intracellular mitogen-activated protein kinase (MAPK) pathway that is involved in melanoma pathogenesis." (PMID 40867317, 2025). "Using multi-color single molecule localization microscopy (PALM and dSTORM), we resolved the mutual nanoscale organization of NRas, PI3K, and BRAF at the plasma membrane of fixed and live melanoma cells." (PMID 41373795, 2025). "While combination BRAF-MEK inhibition has become a cornerstone in treating BRAF-mutant melanoma, ongoing research is focused on its optimal role in the adjuvant setting, particularly in comparison with adjuvant immunotherapy." (PMID 40861441, 2025). "BRAF inhibitor-resistant melanoma cells show changes in lipid metabolism, with lower levels of saturated fatty acids and higher levels of mono/polyunsaturated fatty acids." (PMID 41170386, 2025). "For example, miR-211, miR-205, and miR-200c, which are often downregulated in BRAF-mutant melanoma, normally act as tumor suppressors by targeting oncogenic pathways." (PMID 40872623, 2025). "In the case of iCCA, given its high intra-tumor heterogeneity and complex pathobiology, it cannot be defined as oncogene-addicted to ERK1/2 hyperactivation in the same way as BRAF-mutant melanoma." (PMID 40723336, 2025). "Overall, trametinib represents a cornerstone of targeted therapy for MAPK-driven cancers, particularly in combination with dabrafenib for BRAF-mutant melanoma." (PMID 41302945, 2025). "Genetic mutations in KRAS, NRAS, and BRAF were frequently observed in both melanoma and CRC, whereas BRCA2 and CDKN2A mutations were specific to melanoma." (PMID 40447784, 2025).